BRCA1 (BRCA1 DNA repair associated)
Diseases named in the same sentence as BRCA1 in open-access papers (continued):
Sharing a sentence is not in itself a finding about the gene and the disease.
breast cancer (continued). "For example, SNVs in BRCA1 exons encoding RING and BRCT domains might disrupt BRCA1 expression and function, therefore increasing breast cancer risks." (PMID 40464376, 2025). "Moreover, patients with BC and germline mutations in the breast cancer genes 1 or 2 (BRCA1/BRCA2), (gBRCAm), who are typically young women, often require more aggressive therapeutic interventions." (PMID 40805203, 2025). "BRCA1 is associated with early-onset breast cancer and familial breast cancer syndrome." (PMID 39796173, 2025). "These biomarkers include and are not limited to germline breast cancer gene 1/2(BRCA1/2) mutation (gBRCAm) in HER2-negative, programmed death-1 ligand (PD-L1) status in TNBC and phosphatidyl inositol-4,5-bisphosphonate 3-kinase catalytic sub-unit alpha (PIKA3CA) in ER/PR+ HER2-negative cancers." (PMID 38338854, 2024). "Female carriers of BRCA1/2 genes have an increased lifetime risk of breast cancer." (PMID 37458196, 2024). "In addition to known cancer variants, such as breast cancer-related BRCA1/BRCA2, our study highlights novel associations that should be considered in cancer susceptibility screenings." (PMID 39132489, 2024). "For this reason, acerola leaf extracts may be an important part of nutritional prevention for people at high risk of developing breast cancer, i.e., those with identified mutations in the BRCA1 and BRCA2 genes, or those with a family history of breast cancer." (PMID 38396766, 2024). "In fact, over 75% of female breast cancer patients with BRCA1 mutation exhibit a TNBC phenotype." (PMID 38182557, 2024). "It is essential to examine whether genetic predispositions to breast cancer, such as mutations in BRCA1/2 and other high-penetrance genes, modulate the effects of artificial sweeteners." (PMID 39767777, 2024). "In addition to having an increased risk of developing a first breast cancer, women with a BRCA1/2 genetic mutation and who have been treated for breast cancer are also at an increased risk of having a local recurrence or a second primary cancer." (PMID 39192282, 2024). "As a result, ISGs are expressed in BRCA1/2-deficient tumor cells and stimulate T-cell infiltration and activation, ultimately leading to tumor eradication in BRCA1/2-deficient mouse models of ovarian and breast cancer." (PMID 38473997, 2024). "More patients with breast cancer are undergoing germline BRCA1/2 variant testing." (PMID 38916888, 2024). "However, due to the low incidence of BRCA1/2 mutations in breast cancer patients, relying solely on genetic mutations to identify responsive populations results in a limited potential population." (PMID 39334297, 2024). "However, the clinical utility of PARPi in breast cancer management is limited only to those patients with germline BRCA1/2 mutation, which accounts for only a small percentage (approximately 5–10%) of all breast cancer cases." (PMID 38993666, 2024). "Breast cancer is associated with genetic mutations in specific genes such as BRCA1 and BRCA2." (PMID 39096427, 2024). "Additionally, 202 patients had previously been diagnosed with breast cancer, with 141 being carriers of the BRCA1 mutation and 61 carrying the BRCA2 mutation." (PMID 39594243, 2024). "Since BRCA1/2 mutations are associated with both breast and prostate cancers, the increased risk of prostate cancer in male breast cancer survivors could be due to their germline susceptibility." (PMID 38717807, 2024).
breast cancer (continued). "BRCA1 promoter hypermethylation is linked to higher risk of breast cancer and aggressiveness." (PMID 39684874, 2024). "Moreover, systemic administration of STING agonist combined with PARPi enhances anti-tumor immunity regardless of STING expression in tumor cells and has shown significant therapeutic effect in BRCA1-deficient breast cancer mouse models." (PMID 37588193, 2024). "In conclusion, we have devised AcornHRD, an HRD score algorithm that surpasses clinical variables or BRCA1/2 mutation status in effectively identifying tumors with a higher probability of responding to anthracycline-based neoadjuvant therapy in Chinese breast cancer patients." (PMID 39014466, 2024). "Thus, homologous recombination repair is defective in breast cancers with germline P/LP BRCA1 or BRCA2 variants." (PMID 39507757, 2024). "Given the significance of BRCA1 mutations in the development and progression of breast cancer, these findings have potential prognostic and therapeutic implications for clinical breast cancer management." (PMID 39472438, 2024). "In this cohort of young breast cancer patients, 14 % were BRCA1 or BRCA2 P/LP variant carriers, which stands in accordance with other reports, including one published by the group, showing a 16.5 % BRCA mutation prevalence among 79 luminal breast cancer young patients (below 36 years)." (PMID 39208653, 2024). "One explanation could be that the point of time at which RRBSO was performed was too late to attenuate breast cancer risk in this cohort, as the mean age of breast cancer onset is younger for BRCA1 than for BRCA2 pathogenic variant carriers." (PMID 38892081, 2024). "Breast cancer is predominantly an age-related disease, with aging serving as the most significant risk factor, compounded by germline mutations in high-risk genes like BRCA1/2." (PMID 38275872, 2024). "In addition to the germline mutations implicated in familial breast cancer, somatic BRCA1/2 mutations are also detected in some sporadic cases of breast cancer." (PMID 38956205, 2024). "Her mother was diagnosed with breast cancer at age 36 years, and she was a BRCA1 mutation carrier." (PMID 38256500, 2024). "Although studies from India suggest a higher occurrence of germline BRCA1/2 mutations among breast cancer cases, it is uncertain whether this finding can be generalised to other LMICs." (PMID 39421188, 2024). "Pathogenic variants in BRCA1/2 explain ∼20% of familial clustering of breast cancer cases." (PMID 39438962, 2024). "A well-studied genetic alteration in breast cancer is the BRCA1 gene mutation." (PMID 38256428, 2024). "Our positive results regarding the Korean NIC expansion could serve as a potential model for other nations aiming to improve early detection and personalized treatment for breast cancer patients with BRCA1/2 mutations." (PMID 38791944, 2024). "Although preliminary, findings of this study indicate that FCR is highly prevalent in women who have had breast cancer and are carriers of a BRCA1/2 genetic mutation, even after undergoing preventive surgery, procedures that are known to significantly reduce the risk of recurrence." (PMID 39192282, 2024). "The cells of origin of BRCA1-associated mammary tumours, the mammary luminal epithelial estrogen receptor (ESR1)-negative stem/progenitor population, express the c-KIT (or KIT) receptor tyrosine kinase at high levels, as well as its downstream pathway member, the SRC-family kinase LYN." (PMID 38149669, 2024). "Notably, a mutation in the BRCA1 gene is associated with a 60–80% likelihood of developing breast cancer in women." (PMID 38398090, 2024). "The Korean health insurance policy was updated in July 2020, to include TNBC patients aged 60 or under for BRCA1/2 mutation testing, and the currently applied 10th Korean clinical practice guideline for breast cancer has identical BRCA1/2 mutation testing recommendations for TNBC patients." (PMID 38689097, 2024).
breast cancer (continued). "Familial breast cancer often involves inherited mutations in BRCA1, BRCA2, and other genes." (PMID 39479021, 2024). "Bilateral breast cancer has been identified as an independent predictor for BRCA1/2 mutation." (PMID 38167124, 2024). "It was reported that breast cancer patients with BRCA1 mutation have a high-level iCAF signature." (PMID 38182557, 2024). "This retrospective case-control study presents the screening of BRCA1 variants and predicted impact of these identified variants on the function of BRCA1 along with if any dysregulation of transcriptional or post-transcriptional mechanisms in breast cancer." (PMID 38952531, 2024). "Notably, for patients with breast cancer harbouring BRCA1/2 germline mutations, carboplatin proved superior to docetaxel (ORR: 68.0% vs 33.3%, p = 0.03; PFS: 6.8 vs 4.4 months, p = 0.002)." (PMID 38481526, 2024). "Thus, PARP inhibitors are effective in the therapy of patients with BRCA1/2mut breast cancer and homologous recombination deficiency (HRD)." (PMID 39080120, 2024). "Approximately 5%–10% of breast cancer cases stem from germline mutations in BRCA-1/2 genes." (PMID 39421188, 2024). "Interestingly, 22% of sporadic breast cancers stained positive for THRβ, while a much higher proportion (53%) of the BRCA1-mutated tumors stained positive for THRβ." (PMID 38785457, 2024). "While 5-10% of breast cancers are due to inherited disease causative alleles and mutations in the BRCA1 and BRCA2 genes, the vast majority of cases have a more complex etiology that is not confined to genetics and does not involve major single-gene risk factors." (PMID 39346726, 2024). "For females with a hereditary predisposition for breast cancer caused by a pathogenic germline variant in BRCA1/2, it has been shown that lifestyle and hormonal risk factors could affect their breast cancer risk." (PMID 38473316, 2024). "Likewise, PARP inhibitors were also trialed in the treatment of patients with early-stage breast cancer of BRCA1/2 pathogenic or likely pathogenic variants." (PMID 38730701, 2024). "In this genetic association study of 4121 patients with cancer and 5631 healthy controls, protein-truncating variants in the 5 major genes for breast cancer, particularly BRCA1/2 and PALB2 variants, were significantly associated with the occurrence of interval cancer." (PMID 38270937, 2024). "Previous studies support a high prevalence of BRCA1/2 mutational LOH in breast cancer." (PMID 38869771, 2024). "Recently, HMMR has been proposed as a risk modifier gene for breast cancer BRCA1 carriers." (PMID 39365797, 2024). "This has been shown especially in models of BRCA1 mutated breast cancer." (PMID 38836929, 2024). "An alternative approach (strategy #2) could entail discontinuing the ascertainment of family history of breast cancer and instead refer all women with a pathogenic variant in BRCA1, BRCA2, PALB2, ATM, and CHEK2 or a PRS in the top 10%." (PMID 39669587, 2024). "Based on the “Two-Hit” theory, the DDR PVs can function as the first hit in initiating the oncogenic process, as exampled by BRCA1 PVs that damage the double-strand DNA break repairing function of homologous recombination pathway leading to high risk of breast cancer." (PMID 38575974, 2024). "Defects in BRCA1 are significantly correlated with the risk of breast cancer." (PMID 38244572, 2024). "Studies have suggested that AMH levels might be reduced at the time of diagnosis in some cancer types, including lymphomas and breast cancer patients with BRCA1 mutations." (PMID 38400669, 2024). "Therefore, our team used second-generation sequencing to detect whole-exon susceptibility gene mutations and mutations in four breast cancer susceptibility genes (BRCA1, BRCA2, PALB2, and RECQL) in Chinese women." (PMID 38439896, 2024).
breast cancer (continued). "In addition, SPI1 and another proposed pleiotropic factor, ZFPM1/FOG1 (which is linked to BRCA1-associated breast cancer and eosinophil counts, among other blood traits), are involved in the lineage commitment of eosinophils." (PMID 38308367, 2024). "Genetic testing is crucial in precision medicine for breast cancer, focusing on genes such as BRCA1 and BRCA2 to detect mutations that may raise breast cancer risk." (PMID 39590319, 2024). "The tumor suppressor gene, BRCA1, a substrate of the ataxia-telangiectasia mutated (ATM) gene product, is part of a complex of molecules in the repair of DNA double-strand breaks (DSBs), and loss of BRCA1 contributes to progression of both, sporadic and inherited breast cancers." (PMID 39008483, 2024). "Interestingly, STING agonists can promote PARPi sensitivity by reprogramming TAMs to a dominant pro-inflammatory phenotype in BRCA1-deficient breast cancer models." (PMID 38802355, 2024). "Additionally, young women who develop breast cancer under the age of 40 (YWBC) harbor deleterious germline mutations in BRCA1 (gBRCA1m) or BRCA2 (gBRCA2m) in approximately 12% of cases." (PMID 38398129, 2024). "Furthermore, breast cancers with BRCA1 mutations have earlier onset, more aggressive behavior, and a higher risk of recurrence." (PMID 38499540, 2024). "The age-adjusted HRs for breast cancer mortality associated with entering an MRI surveillance program were 0.20 (95% CI, 0.10-0.43; P < .001) for women with BRCA1 sequence variations and 0.87 (95% CI, 0.10-17.25; P = .93) for women with BRCA2 sequence variations." (PMID 38421676, 2024). "A study of over 20,000 women with breast cancer identified care beyond guidelines through high rates of risk-reducing surgery, specifically bilateral mastectomy, in women with GPVs in breast cancer-associated genes other than BRCA1/2 (95% CI, 37.7−48.5%)." (PMID 39062660, 2024). "This cohort study assesses whether time between most recent childbirth and breast cancer diagnosis is associated with mortality among patients with young-onset breast cancer and germline BRCA1/2 pathogenic variants." (PMID 38639936, 2024). "Additionally, BRCA1/2 mutations in human breast cancer tumors correlate with a characteristic structural variant signature and mutation signatures 3 and 8, without increasing the overall mutation burden." (PMID 39360631, 2024). "The phase III OlympiA trial, which demonstrated increased survival with olaparib for patients with early-stage BRCA1/2-mutated breast cancer, administered olaparib after the completion of adjuvant radiation therapy, thus providing no information on the safety of concurrent treatment." (PMID 38799106, 2024). "This phenomenon suggests that these mutation types have a dominant negative effect, and BRCA1 could still be downregulated in the breast cancers bearing these USP4 mutations." (PMID 38734703, 2024). "The study included 2482 BRCA1/2 mutation carriers and found that enhanced surveillance with annual breast MRI scans and mammography resulted in a higher likelihood of detecting early-stage breast cancers." (PMID 38791944, 2024). "Considering breast cancer-associated mutations across a broader range of genes (BRCA1, BRCA2, PALB2, and the more moderate-risk genes, ATM and CHEK2), the average carrier risk is equivalent to the top 3% of the PRS distribution (see S1 File for definition of mutation carriers)." (PMID 39292644, 2024). "The BRCA1/2 genes are well-studied tumour suppressors, and mutations in these genes have been shown to promote oncogenesis for breast cancer in particular, but have also been associated with ovarian cancer and to a lesser extent prostate and endometrial cancers." (PMID 39282472, 2024). "These genes include BRCA1, whose mutations are well-known contributors to breast cancer." (PMID 39065193, 2024). "Additionally, three women with germline mutations in BRCA1 also had breast cancer (women 9, 10, and 13)." (PMID 38641594, 2024).
breast cancer (continued). "BRCA1 mutations are associated with 20%–25% of breast cancers." (PMID 39282472, 2024). "A former prospective multi-center cohort study reported a notable decrease in breast cancer risk in both BRCA1 and 2 pathogenic variant carriers associated with RRBSO, resulting in a decrease in breast-cancer-specific mortality of more than 50% (HR = 0.44; 95% CI, 0.26–0.76)." (PMID 38892081, 2024). "Additionally, mammography detected 33% of breast cancers in BRCA1 mutation carriers and 43% in BRCA2 mutation carriers." (PMID 38791944, 2024). "Interestingly, variants in exon 9 of BRCA1 are significantly associated with the development of mammary tumours in dogs." (PMID 38787171, 2024). "Nonetheless, research suggests that these modifications have a range of effects on BRCA1 and may potentially increase the risk of breast cancer by affecting its binding to proteins such as CtIP, ABRAXAS1, and BACH1-P." (PMID 38543119, 2024). "Additionally, the hypermethylation of the -132 site in the PEMT promoter occurs in breast cancer type 1 susceptibility gene (BRCA1)-mutated breast cancer cells, resulting in reduced enzyme expression." (PMID 39409074, 2024). "Talazoparib is used in patients with advanced breast cancer and a germline BRCA1/2 mutation." (PMID 38167124, 2024). "Advanced diagnostics and biomarker research are also central to the utilization of quantum dots in breast cancer, focusing on the early detection of mutations, such as those in the BRCA1 gene, and the quantitative analysis of cancer-related proteins like IGF1R." (PMID 38730959, 2024). "The downsides—future breast cancer events—for patients with BRCA1/2 variants undergoing BCT may be overstated." (PMID 38916888, 2024). "One diagnostic tool for breast cancer is the BRCA1/2 genetic testing and counseling." (PMID 39011181, 2024). "For a hypothetical cohort of 10,000 BRCA1 mutation carriers, 10 years of continuous combined oral contraceptive use resulted in 99 additional cases of breast cancer by the age of 35 years, in addition to the 572 cases expected for women with no use of oral contraceptives." (PMID 38892081, 2024). "While low-level mosaic constitutional epimutations are detected also in WBC in individuals harboring gBRCA1 PV, BRCA1 mutations and epimutations seem to be mutually exclusive in breast cancer tissue, indicating mutations and epimutations to be independent underlying risk factors." (PMID 40225940, 2024). "Besides that, 90% of BC is caused by somatic mutations acquired lifelong; in BRCA1/2 PV carriers, there is an increased lifetime risk of developing breast cancer." (PMID 38540206, 2024). "The National Comprehensive Cancer Network Clinical Practice Guidelines in Oncology (NCCN Guidelines) includes two primary levels of risk assessment, evaluating extended genetic risk factors followed by clinical characteristics as well as family history of breast cancer for BRCA1/2 mutation carriers." (PMID 38543119, 2024). "We hypothesized that epigenetic age acceleration observed in blood cells may be associated with BRCA1 epimutations and germline mutations, both of which have been shown to increase risk of breast cancer." (PMID 39529133, 2024). "BRCA1-mutated and/or basal-like breast cancer cells, characterized by compromised base-excision repair mechanisms of oxidative DNA damage, exhibit heightened sensitivity to the therapeutic effects of elesclomol, which enhances oxidative stress-induced cell death." (PMID 39867656, 2024). "Additionally, the third pathway with the highest number of overlapping genes was found regarding the BCRA1-Pearson correlation coefficient (PCC) network, this model being potentially associated with breast cancer and the BRCA1 mutations effect." (PMID 39125744, 2024). "A total of 938 (37.3%) BRCA1/2 mutation carriers developed breast cancer." (PMID 38800375, 2024).